TNF (tumor necrosis factor)
Diseases named in the same sentence as TNF in open-access papers (continued):
Sharing a sentence is not in itself a finding about the gene and the disease.
tumor (continued). "Pro-inflammatory cytokines, such as TNF, IL-1β, and IFN-γ, are released by the tumor–host interaction and can reach the hypothalamus, inducing a depression-like behavior." (PMID 31035457, 2019). "Because TNF-α plays a key role in the development of CAC, we examined the anti-tumor effect of MA-35 by inhibiting TNF-α signaling in AOM/DSS mouse model." (PMID 31484999, 2019). "At 0.5 μg, TNFα‐CSG led to a significant increase in intratumoral CD8+ T cells and macrophages (CD11b+ F480+ Ly6G−) but reduced the population of tumour myeloid‐derived suppressor cells (CD11b+ F480− Ly6G+) (Fig EV3C)." (PMID 31709774, 2019). "One promising protein vector is the tumor necrosis factor (TNF)-related ligand (TRAIL), a type 2 transmembrane protein 30, which is able to trigger tumor cell death 31, 32 through apoptosis." (PMID 31534529, 2019). "In this study, we observed that TNF-α/TNFR2 signaling promotes Th9 cell differentiation and increases the antitumor capability of tumor-specific Th9 cells." (PMID 30717817, 2019). "In the tumor microenvironment, TGF-β, Chemokine 4/12 (CXCL4/12), interleukin-6 (IL-6) and tumor necrosis factor-α (TNF-α), etc. can enhance EMT." (PMID 31195692, 2019). "Two main effector functions of NK cells against tumor cells are direct cytotoxic effect by releasing cytoplasmic granules (Perforin and Granzyme) and cytokine secretion such as IFN-γ and TNF-α." (PMID 31870124, 2019). "In summary, TNFα‐CSG has the dual capacity to promote immune cell entry and ECM degradation within the tumour." (PMID 31709774, 2019). "Noteworthy, CD4+ T cells are critical for expansion, trafficking and functioning of cytotoxic CD8+ and memory T cells, an effect known as “CD4+ T-cell help” fostering tumor destruction through cytokine signaling, especially IFN-γ and TNF-α." (PMID 31812953, 2019). "The formation of osteolytic lesions is mediated by osteoclasts via the release of multiple osteoclastogenic factors from tumor cells (e.g., IL-1, IL-6, IL-11, PDGF, MIP1α, TNF, M-CFS, RANKL and PTHrP)." (PMID 30823602, 2019). "First, we found that in TNFα-stimulated MDA-MB-231:MSC “Contact” co-cultures, the tumor cells acquired very elongated morphology (Figure 9A1) which is typical of cells that express high motility capabilities." (PMID 31031757, 2019). "Secondly, we analyzed the amount of key effector molecules – IFN-γ, TNF-α, perforin and granzyme B – that are induced by NK101 or NK-92 after tumor cell co-culture." (PMID 31126350, 2019). "This has developed a curiosity in scientific community to understand the molecular signaling pathways that connect TNF-α with the development and survival of CRC tumor cells." (PMID 30509964, 2019). "TNF increases the number of MDSCs and neutrophils in the TME, leading to increased tumor growth, angiogenesis, and amplification of inflammation." (PMID 32039025, 2019). "TNFα stimulation triggered production of MCP-1 by macrophages and also by tumour cells of different origins." (PMID 30956175, 2019). "In a previous work, one of us (MMG) found tumor infiltrating T cells in human PDAC, particularly CD4 (helper) T cells, producing tumor necrosis factor (TNF)-α and interleukin (IL)-17A." (PMID 31540511, 2019). "Taken together, our results indicated that pro-inflammatory genes like VEGF, TNF-α are up-regulated while tumor suppressor genes like p27, MKP-1 are down-regulated in tumor samples as compared to normal controls." (PMID 31023373, 2019). "Inflammatory cytokines such as tumor necrosis factor-alpha (TNF-α) and interleukins 1, 6 and 8 (IL-1/6/8) may interfere with the function of natural killer cells, cytotoxic T-lymphocytes, and antigen-presenting cells, which promote the growth and metastasis of tumor cells." (PMID 31443699, 2019).
tumor (continued). "PD-L1 upregulation can be motivated by cytokines induced by tumor-infiltrating immune cells, including interferon (IFN), tumor necrosis factor (TNFalpha), interleukin (IL-4), and vascular endothelial growth factor (VEGF) etc.." (PMID 31039792, 2019). "However, albeit the limited direct oncolysis, cytokines like IFNγ, TNFα and IFNβ, induced in the tumor tissue early after VSV‐GP treatment, are known to be able to induce apoptosis and may be involved in the increased caspase‐3 staining seen in the tumor tissue." (PMID 30972741, 2019). "In tumor tissue in the CC group, ANGPTL-4 showed a significant positive correlation with IL-1β (p < 0.01), a positive correlation with TNF-α (p ≤ 0.05), and a positive correlation with NFκB (p < 0.05)." (PMID 31741709, 2019). "Meanwhile, immune response to the tumor was enhanced by promoting tumor-infiltrating M1 macrophages in the spleen, which secreted higher levels of IL17A in the spleen and TNF-α in the tumor." (PMID 31775255, 2019). "IL-2, TNF-α, and IFN-γ immune factors enhanced the function of tumor-killing cells such as CD3+CD4+T and NK cells." (PMID 31256187, 2019). "The first one is increased in TAMs in human PDAC and its inhibition will repolarize TAMs and increase MHC class II, TNF-α and INF-γ expression besides reducing tumor growth." (PMID 31998254, 2019). "To determine the functional consequences of tumor-stroma-inflammation networks, we first determined the ability of factors released by TNBC:MSC co-cultures stimulated by TNFα to promote processes involved in angiogenesis." (PMID 31031757, 2019). "The expression of Th1 cytokines (IL-2, TNF, IFN-γ) and Th2 cytokines (IL-4, IL-5, IL-6, IL-10) were examined in frozen tumor tissues from 80 GC patients by ELISA." (PMID 31417548, 2019). "To evaluate CSG as a carrier molecule for TNFα delivery to tumour ECM, we produced bacterial recombinant TNFα with carboxy‐terminal CSG peptide (molecular weight 18.9 kDa)." (PMID 31709774, 2019). "In the tumor microenvironment, a variety of inflammatory mediators, such as cytokines (IL-6, IL-10, VEGF, TNFα, and TGFβ), chemokines (CCL20 and CXCL8) as well as lipid mediators (such as PGE2) are continuously produced." (PMID 31100828, 2019). "The prominent role of death ligands Tumor necrosis factor (TNF)-α, TNF-related apoptosis inducing ligand (TRAIL) and CD95-L in tumor biology is undoubted, yet not fully understood." (PMID 31555275, 2019). "Both Lipoxins and their stable analogues exert biological effects, such as antiangiogenic property, by binding to FPRs, inhibiting the secretion of some mediators, such as TNF-α, VEGF and MMPs, leading to inhibition of the cell proliferation and tumour growth." (PMID 30862840, 2019). "Further, systemic administration of TNFα coupled to ACDCRGDCFCG-peptide, a ligand for αVβ3-integrin, has enabled targeting the tumor vasculature and inducing anti-tumor effects in tumor-bearing mice." (PMID 31231358, 2019). "Under both experimental conditions, disrupting endothelial ICAM-1/tumor LFA-1 interaction results in a dramatic reduction in the secretion of IL-1β, IL-6, PGE2 and TNFα into the co-culture supernatant." (PMID 31511625, 2019). "M1 macrophages have antineoplastic effect with the function of secreting tumor necrosis factor-α (TNF-α), IL-23, IL-12, etc., while M2 phenotype will express IL-10, CCL20, transforming growth factor-β (TGF-β), etc., to promote tumor." (PMID 31395836, 2019). "Our results, thus, provide evidence of the successful combination of prophylactic TNF neutralization with ICB therapy strategy to ameliorate toxicities, while keeping or even ameliorating anti-tumor efficacy." (PMID 31309173, 2019). "Within the tumor microenvironment, IL-1β acts as a pleiotropic cytokine, increasing tumor growth and invasiveness via induction of MMPs, VEGF, IL-8, IL-6, TNFα, and TGFβ." (PMID 31174326, 2019).
tumor (continued). "It was demonstrated that HSP72 and HSP105 expressed on the surface of tumor-derived EVs promoted DCs to produce high levels of pro-inflammatory cytokines (IL-6, PGE2, IL-1β, TNF-α) in a TLR2- and TLR-4–dependent manner." (PMID 31680949, 2019). "Similar to tumor cells, TNFRSF1B protects immunosuppressive regulatory T (Treg) cells and myeloid-derived suppressor cells (MDSC) from the death-inducing TNF and thus enhances the proliferation and function of those tumor-promoting cells." (PMID 32039005, 2019). "EGFR-expressing effector T cells proliferate better and produce more IFN-γ and TNF-α in the presence of EGFR ligands produced by tumor cells in vitro and exerted stronger antitumor response delaying tumor growth in vivo." (PMID 31921216, 2019). "TNF-α, TRAIL and the FasL-mediated/TRAF2/NF-κB survival pathway can protect tumor cells from cell death." (PMID 31462894, 2019). "Expression levels of perforin, granzyme B, IFN-g, TNF-a, and IL-2 in CD8+ tumor-infiltrating lymphocytes (TILs) were significantly lower than those in CD8+ T cells of peripheral blood." (PMID 30682105, 2019). "CD8+ T cells are activated to release tumor necrosis factor (TNF) and to become cytotoxic T cells (CTL) that kill tumor cells." (PMID 30909630, 2019). "And the expression of IL‐6, IL‐1β, TNF‐α and MMP9 in tumor samples were also markedly up‐regulated compared with non‐tumor parts." (PMID 30903649, 2019). "Considering B7-H3 can induce tumor necrosis factor-alpha (TNF-α) expression in monocyte-macrophage cells, we assume that B7-H3 is likely to promote the production of some cytokines to influence tumor progression through interaction with CD68-positive cells." (PMID 30813210, 2019). "The persistent production of pro-inflammatory cytokines such as IL6, tumor necrosis factor (TNF) and IL1 within the tumor and its microenvironment plays a key role in mediating the tumor-promoting effect of inflammation." (PMID 31878932, 2019). "Pro- tumor neutrophils induce progression disease and release of CXCL1, MMP9, VEGF, and TNFα, whose reduction suppresses tumor growing." (PMID 31799175, 2019). "Rnf5−/− tumor-infiltrating CD4+ and CD8+ lymphocytes (TILs) also displayed greater effector function, including enhanced IFN-γ, TNF-α, and IL-2 production." (PMID 30940817, 2019). "The vaccine showed efficient tumor eradication in several tumor models with enrichment of IFN‐γ+, TNF‐α+, and granzyme B+ tumor‐infiltrating lymphocytes." (PMID 30937265, 2019). "Taken together, these results suggest that TNF-α production by TRIM59-/--M2 macrophages promotes the expression of MMP-9 and Madcam1 in B16-F0 and B16-F10 tumor cells, enhancing their metastatic potential." (PMID 31600735, 2019). "Increased expression of TNFα results in a prolonged and sustained activation of NF-κB and STAT3 signaling thus activating several tumor cell resistance mechanisms in GSCs." (PMID 30854231, 2019). "High plasma levels of IL-6, TNFα, and γ-INF have been observed in both tumor-bearing animals and cachectic cancer patients." (PMID 30833900, 2019). "In cancer cachexia, various tumor and host factors influence skeletal muscle mass homeostasis: e.g., proteolysis-inducing factor (PIF) and cytokines, such as TNF-α, and IL-6." (PMID 30754663, 2019). "As neutrophils produce PGE2via COX‐2, these results together indicate that neutrophils self‐amplify their recruitment through the TNF‐α‐primed PGE2‐EP2‐NF‐κB‐CXCL1 pathway and recruited neutrophils amplify inflammation for tumour development." (PMID 30381825, 2019). "By blocking TNFα both studies showed an increase in CD8+ T cells numbers and viability in the tumor microenvironment and draining lymph nodes." (PMID 31439050, 2019). "Another important cytokine, TNFα, which is known to impair TGF-induced T-reg function was found to reduce in the tumor microenvironment of CD47−/− 3BD9 tumors." (PMID 31882679, 2019).
tumor (continued). "The developed agent, TNFα‐CSG, has dual capacity as an immunotherapeutic and ECM reducing agent which improves tumour perfusion and drug delivery." (PMID 31709774, 2019). "For example, it was found that a SMAC mimetic monotherapy is effective only in a small number of tumor cell lines (< 15%), whereas in combination with exogenously added TNFα or TRAIL, around 50% of the tumor cell lines died." (PMID 31412918, 2019). "By secreting cytokines such as IL-6, IL-18, TNF-α, TNF-β, IL-1β, IFN-γ and IL-23, arginase 1 (ARG1) and ECM-modifying enzymes into the TME, TAMs contribute to tumor cell growth, angiogenesis, invasion and metastasis." (PMID 30781344, 2019). "We have elucidated the role of MK2 in regulating the mRNA turnover by reporting that MK2 controls the stability of TNF-α, VEGF, p27 and MKP-1 transcripts in tumor microenvironment." (PMID 31023373, 2019). "TNF- α, IL-1, TGF-β, and IL-6 are able to induce the expression of many angiogenic growth factors in tumor such as vascular endothelial growth factor (VEGF)." (PMID 30642295, 2019). "The immune‐enhancing effects of TNFα‐CSG translated into therapeutic benefits as shown by reduced tumour growth and enhanced survival in tumour‐bearing mice with an intact immune system." (PMID 31709774, 2019). "In contrast, while antibody therapy only modestly increased IFN-γ-producing CD4+ T cells in the tumor, tritherapy significantly increased IFN-γ+, TNF-α + and IFN-γ + TNF-α + CD4+ T cells compared to all other treatments." (PMID 31747946, 2019). "Although TNFR1 was responsible for TNF-α-induced systemic and anti-tumor effects, several lines of evidence demonstrated that TNFR2 rather than TNFR1 mediates cytotoxic and inflammatory actions of TNF-α in CDDP-injured kidneys." (PMID 30866950, 2019). "NRG-TNF is a drug consisting of the human TNFα protein fused to the CNGRCG peptide that targets it to aminopeptidase N (CD13), an enzyme overexpressed on newly formed tumor endothelial cells." (PMID 31440262, 2019). "Various chemokines were increased in TNF-α-activated MSCs and among them, CXCR2 ligands (CXCL1, CXCL2, and CXCL5) efficiently recruited CXCR2+ neutrophils into the tumor and were responsible for its pro-metastatic effect." (PMID 31130595, 2019). "Consistent with pathological features, there was significantly higher expression of cytokines IL-6 (Il6) and TNFα (Tnfa), chemokines KC (Cxcl1), MIP2 (Cxcl2), and MCP1 (Ccl2), and tumor-promoting molecule COX2 (Cox2) in Nlrp12-/- HCC." (PMID 30990169, 2019). "Early production of TNF-α, IL-1β, and IL-6 in the liver after DEN treatment correlated with tumor development in AIRmax mice." (PMID 31049358, 2019). "In our studies, we found that GFPT2 is transcriptionally upregulated in response to TNF, or combinations of TNF and TGFβ treatments, suggesting that GFPT2 expression is upregulated in response to inflammatory cytokines present in the tumor microenvironment." (PMID 30885209, 2019). "TANs can alter the tumor microenvironment (TME) by secreting inflammatory cytokines such as IFNγ and TNFα that potentiate the local immune infiltrates and systemic response." (PMID 31131086, 2019). "The results revealed that tumor size ≥1.5 cm, PTV ≥83.7 cm3, AFP ≥25.0 ng/ml, a low level of TNF-α, WBC, baseline and post-treatment TPLC and CLP counts except for post-treatment B cell value, were significantly associated with poor OS (p < 0.05 for each)." (PMID 31552194, 2019). "S. boulardii treatment reduced AOM/DSS-induced UC carcinogenesis in mice, as indicated by the reduced tumor load and reduced TNF-α and IL-6 levels in vivo, as well its effects on TNF-α and IL-6 activities in vitro." (PMID 31694526, 2019).
tumor (continued). "Factors are involved in stimulating tumor angiogenesis indirectly by inducing VEGF, TGF-α and β, TNF-α, keratinocyte growth factor, insulin-like growth factor I (IGF-I), FGF, PDGF, and cytokines [interleukin (IL)-1α and IL-6 and EGF on tumor cells]." (PMID 31303863, 2019). "In this study, we use a new biological agent, so‐called TNFα‐CSG, an immune‐modulating cytokine that is specifically targeted to tumour ECM." (PMID 31709774, 2019). "In contrast, lymphocytes enhance the anti-tumor efforts by secreting cytokines, such as interferon gamma (INF-γ) and tumor necrosis factor (TNF-α), thereby promoting cytotoxic cell death." (PMID 31620369, 2019). "The treatments induced an obvious increase in cytotoxic cytokine (TNF-α and IFN-γ) levels in tumor tissues." (PMID 31350406, 2019). "The tumor-stroma-inflammation network identified in our study suggests that inhibiting the activities of TNBC-typical pro-inflammatory cytokines, such as TNFα and IL-1β would halt tumor-stroma interactions that stand in the basis of TNBC progression." (PMID 31031757, 2019). "It is known that NK-cells in the human body play a role in innate immunity by detecting and killing virus-infected cells, tumor cells, and abnormal cells and that activated NK-cells promote the release of cytokines such as IFN-γ and TNF-α." (PMID 30925876, 2019). "Aside from the classical cytotoxic mediators (e.g., granzymes), death ligands TNF, CD95, and TRAIL are used by the different γδ T cell-subsets to lyse a broad range of tumor cells." (PMID 31555275, 2019). "The concentrations of pro-inflammatory cytokines such as IL-12, TNF-α, and IFN-γ were higher in the ascites of tumor-bearing mice receiving chemotherapy combined with anti-BTLA Ab (Fig. 2f1-f3)." (PMID 31753019, 2019). "Smad7 over-expression in T cells promotes infiltration of the tumor environment by Tbet/RAR-related orphan receptor (ROR)-γt double-positive CD4 T cells, which produce high levels of tumor necrosis factor (TNF)-α and IFN-γ, but lower levels of IL-17A." (PMID 31052449, 2019). "For example, anti-TNF-α antibodies and antagonists of IL-1 and IL6 receptors exhibit anti-tumor effects in pre-clinical models of PDAC." (PMID 31277269, 2019). "These cells produce high levels of IFN-gamma and TNF-alpha upon stimulation through CD1646 and have a role in tumor immunosurveillance." (PMID 31462637, 2019). "M1 macrophages play critical roles in innate host defense and killing tumor cell by producing reactive oxygen/nitrogen species (ROS/RNS) and pro-inflammatory cytokines such as IL-1β, IL-6, tumor necrosis factor α (TNF-α)." (PMID 31629410, 2019). "Three fractions of RT increased the concentrations of seven inflammatory mediators in tumor tissues: GM-CSF, IL-17, CXCL1, CXCL2, CCL2, CCL5 and TNFα." (PMID 31752313, 2019). "As well, the expression of members of the tumor necrosis factor (TNF)-family such as FAS ligand (FASL), TNF, and TNF-related apoptosis inducing ligand (TRAIL) induce tumor-cell apoptosis upon formation of immune synapses." (PMID 31035454, 2019). "OT-II Th9 cells and TNF-α-treated Th9 cells were transfused to B16-OVA-bearing C57BL/6 mice, and cells from tumor-draining lymph nodes (TDLNs) were collected and analyzed." (PMID 30717817, 2019). "Next, to evaluate the potential role of GC tumor-derived TNF-α in PD-L1 induction on mast cells, we added neutralizing antibody against TNF-α into TTCS/mast cell co-culture." (PMID 30808413, 2019). "Two SASP components, TNF-α and ICAM-I, were critically required for promoting NK cell surveillance of the drug-treated tumour cells, tumour regression and prolonged survival in the KRAS-mutant lung cancer model." (PMID 30626155, 2019).